CRP (C-reactive protein)
Diseases named in the same sentence as CRP in open-access papers (continued):
Sharing a sentence is not in itself a finding about the gene and the disease.
anemia (continued). "He had severe anemia (Hb = 4 g/dl), leukopenia (1.8 x109/L), elevated CRP (89 mg/dl), elevated erythrocyte sedimentation rate (ESR = 42 mm/hr), and a normalizing urine protein to creatinine ratio (0.041 g/mmol)." (PMID 38760753, 2024). "Laboratory tests revealed mild anemia, a high neutrophil count, elevated fibrinogen and C-reactive protein (CRP), and urinalysis revealed large leukocyturia, hematuria, and proteinuria without detection of nitrites." (PMID 39205739, 2024). "Studies have shown that joint mobility is more severe in RA patients with anemia, interleukin-6 (IL-6), CRP, and CCP levels are significantly elevated in anemic RA patients compared to non-anemic RA patients, indicating high disease activity." (PMID 39136015, 2024). "We also observed acutely increased concentrations of IL-6 and hepcidin during the acute attack in correlation with the high levels of CRP and severe anemia." (PMID 39408004, 2024). "Laboratory workup revealed normocytic normochromic anaemia (haemoglobin 11.7 g/dL), white blood cell count 7,100/μL, platelet count 170,000/μL, erythrocyte sedimentation rate 62 mm/h and C-reactive protein 33.2 mg/L." (PMID 39044899, 2024). "Laboratory findings showed a progressive increase in C-reactive protein levels and persistence of microcytic hypochromic anemia, probably due to chronic inflammation." (PMID 38669404, 2024). "Multicentric CD (MCD) is less common and clinically symptomatic, characterized by systemic involvement, which presents as anemia, fever, increased C-reactive protein, ESR, and hypergammaglobulinemia." (PMID 38962652, 2024). "All patients in this series experienced fever and rash that involved the palms and soles and had common laboratory abnormalities, including hyponatremia, anemia, thrombocytopenia, transaminitis, and elevated C-reactive protein." (PMID 39387516, 2024). "Most patients (71.3%) displayed a grade 1–2 CRP elevation at initial diagnosis, followed by 44.4% with grade 1–2 anemia and 35.8% with a grade 1–2 LDH elevation." (PMID 38877146, 2024). "Among these latter, the first subphenotype (14% prevalence) was formed by younger patients, with elevated counts of white blood cells (WBC) and platelets, mild anaemia and normal ranges of C-reactive protein (CRP), creatinine and albumin." (PMID 38915125, 2024). "There was a 76% increase in patients with grade 1–2 anemia, while the prevalence of grade 1–2 CRP decreased by 26.32%." (PMID 38877146, 2024). "The remaining laboratory tests showed leukopenia at 2810/μL, normocytic normochromic anemia at 8.5 g/dL, regenerative lymphopenia at 150/μL and C-reactive protein (CRP) at 122 mg/L." (PMID 39852659, 2024). "Blood test findings showed anemia, with a hemoglobin level of 9.0 g/dL, a C-reactive protein (CRP) level of 1.18 mg/dL, and elevated lactic acid at 5.7 mmol/L." (PMID 39147950, 2024). "Blood tests showed hyponatremia, hypoglycaemia, normocytic anaemia, and a slight increase in the CRP levels." (PMID 38888722, 2024). "Frequent laboratory abnormalities included: anemia (98.9%), thrombocytopenia (90.2%), leukopenia (88.3%), C-reactive protein (CRP) elevation (93.1%) and hepatic cytolysis or cholestasis (55.7%)." (PMID 38822396, 2024). "Laboratory tests showed moderate anemia, elevated CRP, elevated serum creatinine, and elevated urea." (PMID 39205739, 2024). "Our findings identified 25 indicators, including Gender, Surgery, Type of surgery, LYM%, MO%, LYM, BLT, TP, ALB, SF, K, CA, CREA, UA, PT, APTT, FIB, D‐dimer, CRP, hs‐CRP, ESR, PCT, IgA, CEA, and CA‐153, as independent risk factors for anemia." (PMID 39621534, 2024). "A 47-year-old woman with a 12-year history of anemia and high C-reactive protein (CRP) levels was admitted to our hospital with worsening fatigue and night sweats." (PMID 39776937, 2024).
anemia (continued). "In daily clinical practice, ESR has been widely replaced by CRP since ESR is affected by several parameters such as anemia and protein levels; meanwhile, ESR measurements remain elevated for a longer period." (PMID 39203582, 2024). "His initial laboratory workup was positive for mild anemia, and slight elevations in lactic acid, C-reactive protein (CRP), and aspartate aminotransferase (AST)." (PMID 39258095, 2024). "Among the studies targeting CKD anemia, in three controlled studies, both hemoglobin and Hct levels showed significant increase, accompanied by a reduction in C-reactive protein levels and an improved total effective rate." (PMID 39338353, 2024). "In logistic regression analysis, anemia was associated with lower levels of Alb and higher levels of WBC, CRP, LDH, and ESR (P < 0.05)." (PMID 38886797, 2024). "While both syndromes can present with fever, shock, elevated CRP, neutropenia, and thrombocytopenia, the presence of hyperferritinemia, anemia, and splenomegaly are more specific to HLH." (PMID 39108977, 2024). "The major laboratory features of pediatric CEAS include iron deficiency anemia (IDA), hypoalbuminemia, and near-normal levels of C-reactive protein (CRP)." (PMID 38890589, 2024). "The laboratory evaluation revealed anemia, neutrophilic leukocytosis, coagulopathy, and elevation of C-reactive protein (CRP) 424.79 mg/L and procalcitonin (PCT) 26.78 ng/mL." (PMID 39295697, 2024). "Laboratory findings in patients with brucellosis often include anemia, leukopenia, thrombocytopenia, elevated liver enzymes, increased CRP, and increased ESR." (PMID 39156452, 2024). "They had more D-dimers (p = 0.005), a lower ADAMTS13 activity (p = 0.002) with higher vWF:Ag/ADAMTS13 activity ratios (p = 0.005), higher CRP levels (p < 0.001) and more anemia (p = 0.02)." (PMID 38915768, 2024). "Inflammation (elevated CRP or elevated AGP), anemia, and vitamin B12 insufficiency were significantly associated with increased odds of preterm birth in unadjusted logistic regression models." (PMID 38267943, 2024). "In univariate analysis, > 3 comorbidities, CRP ≥ 12 mg/L, anemia, low serum albumin, and stages III-IV-V vs. I-II of renal failure were significantly associated with ID." (PMID 38287253, 2024). "Laboratory blood analysis revealed mild anemia (hemoglobin [Hb], 8.4 g/dL); elevated white cell count (white blood cell, 17,700 cells/mL); and C-reactive protein (CRP, 6.25 mg/dL)." (PMID 38165596, 2024). "Except for slight anemia (Hb: 11.8 g/dL) and elevation of CRP level (5.98 mg/dL), her laboratory data was normal, and the levels of tumor makers were also within the normal range." (PMID 39523235, 2024). "In 2019, a 60-year-old man was admitted to the hospital due to recurrent fever, elevated inflammatory markers (including CRP, serum amyloid A and ferritin), macrocytic anaemia, widespread arthralgias and auricular chondritis." (PMID 39251478, 2024). "This sample of children had a high burden of inflammation (62% with CRP > 5 mg/L or AGP > 1 g/L), malaria (13%), anaemia (61%) and inflammation‐adjusted iron deficiency (77%) at enrolment." (PMID 38217291, 2024). "His laboratory assessments were notable for leukopenia, anemia, thrombocytopenia, elevated C-reactive protein (CRP), mildly elevated ALT, normal kidney function, and developed hypotension following admission." (PMID 39240972, 2024). "Initial laboratory evaluation revealed normocytic and normochromic anemia and a slight elevation in C-reactive protein." (PMID 38344603, 2024). "The persistent elevation of CRP and concurrent development of anemia raised suspicions of a hematologic disorder, leading to the diagnosis of non-secretary multiple myeloma." (PMID 39070404, 2024). "CRP, anemia, and hypercalcemia, all of which are related to inflammation and, tumor grade, are independent predictors of serum LRG1 levels." (PMID 38658967, 2024).
anemia (continued). "ID was significantly more frequent in patients with > 3 comorbidities (65.6% vs. 55.9%; p = 0.0274), those receiving a treatment with a possible impact on ID or anemia (60.5% vs. 49.6%; p = 0.0042) or those with CRP ≥ 5 mg (64.8% vs. 49.6%; p < 0.001)." (PMID 38287253, 2024). "We obtained the following parameters: serum creatinine and urea; the inflammation markers CRP (C-reactive protein) and IL-6 (interleukin-6); and the anemia markers complete blood count, serum ferritin, and transferrin saturation (TSAT)." (PMID 39200365, 2024). "Blood analysis presented microcytic hypochromic anemia, aggravated renal function, leukocytosis, and increased C-reactive protein." (PMID 38510889, 2024). "There is growing evidence that wildfire smoke induces inflammation in pregnant women, indicated by elevated CRP, IL8, IL6, MCP-1, neutrophils, and monocytes, and that biofuel exposure in pregnant women from India has been associated with anemia." (PMID 38892681, 2024). "Anemia registered as the most common grade 1–2 adverse event, affecting 87% of patients, followed by elevated CRP in 65.7% and lymphopenia in 44.2% of patients." (PMID 38877146, 2024). "Blood tests showed raised inflammatory markers (WCC and CRP) as well as microcytic anemia, mild hyponatremia, and hypoalbuminemia." (PMID 38962629, 2024). "Our study revealsed that the KDSS group exhibited significantly elevated levels of NLR and CRP along with a more severe degree of anemia." (PMID 39220153, 2024). "Another commonly used predictive model is the CAR-HEMATOTOX score, which captures cytopenias (thrombocytopenia, anemia, neutropenia, etc.)and inflammatory markers (C-reactive protein (CRP), ferritin, etc.)at baseline condition." (PMID 38558801, 2024). "In the current study, CRP levels, anemia, hypercalcemia, and grade were independent predictors of increased LRG1 levels." (PMID 38658967, 2024). "The increased levels of CRP, anemia, and reduced levels of albumin are also due to increased level of IL-6, which leads to myocardial infarction and an extra-articular manifestation of RA." (PMID 37113751, 2023). "Blood work revealed a white blood cell count of 18.7 × 103/dl, a mild anemia, and a creatinine level of 7 mg/l; C-reactive protein (CRP) level was 294.6 mg/l." (PMID 37095582, 2023). "In this study, the correlation between malnutrition, hypoalbuminemia, anemia, elevated CRP, and low transferrin levels, as well as mortality in seniors between 65 and 100 years, should be revealed." (PMID 37892441, 2023). "Women with elevated CRP had 1.7 greater odds for anaemia, compared to their counterparts (OR:1.7, 95% CI: 1.04, 2.8; p ≤0.05)." (PMID 36996088, 2023). "Laboratory findings showed moderate anemia, highly elevated c-reactive protein, and modified coagulation tests." (PMID 37510971, 2023). "Elevated CRP (a sign of acute inflammation) was noted in 319 (72.5%) women and anaemia and inflammation in 93 (21.2%)." (PMID 37020182, 2023). "Investigations showed anemia with a hemoglobin level of 9.2 g/dL, a white blood cell count of 14200/mm3, a C-reactive protein of 112.6 mg/L, and a prothrombin time of 75.1 seconds with an international normalized ratio (INR) of 8.5." (PMID 37162778, 2023). "7% of infants had anaemia, 14% lymphopenia, 4% neutropenia and 4% thrombocytopenia, 75% low CRP level." (PMID 37880789, 2023). "The clinical presentation of our group is in line with previous studies; bloody diarrhea was the most common symptom, and anemia hypoalbuminemia and elevated CRP were the most common laboratory findings." (PMID 36937967, 2023). "Patients with anemia were significantly older (p < 0.0001), reported more co-morbidities, and presented higher baseline levels of procalcitonin, CRP, ferritin and IL-6." (PMID 37270578, 2023). "During hospitalization, hematologic studies revealed anemia, a normal leukocyte count with neutropenia and monocytosis, thrombocytopenia, and elevated C-reactive protein (CRP)." (PMID 37528877, 2023).
anemia (continued). "Multiple laboratory findings (CRP, CRP/Alb, PLR) revealed that DN tumors were associated with systemic inflammation and anemia of chronic disorder (Hb)." (PMID 36127822, 2023). "Laboratory tests revealed high C-reactive protein levels (median: 61 mg/L, range: 14.3–189 mg/L) and anemia (median Hb: 9.35 g/dL, range: 7.6–11.1 g/dL) in all patients." (PMID 37676863, 2023). "A high C-reactive protein (CRP) level is frequent in all the irAEs types (42%) and anemia is a common finding in CIC due to digestive bleeding." (PMID 37511260, 2023). "Anemia, hypoalbuminemia, elevated lactate dehydrogenase, glycated hemoglobin, and C-reactive protein levels are more pronounced in subjects with type two diabetes and cancer." (PMID 37627906, 2023). "This case had a very high CRP level of 211 mg/L, anemia and liver dysfunction, which were considered to be due to GCA, because all of these had improved by day 27 after the start of treatment for GCA." (PMID 38138230, 2023). "Patients with one of these phenotypes had renal failure, hypoalbuminemia, anemia, lymphopenia, and elevated CRP level (median, 9.0 mg/dL), and had the highest likelihood of ICU transfer or in-hospital mortality (59%)." (PMID 37507773, 2023). "Laboratory tests showed neutrophilia and eosinophilia, normocytic anemia and elevated erythrocyte sedimentation rate and C-reactive protein." (PMID 37007396, 2023). "Other inflammatory parameters such as interleukin-6 (IL-6) and C-reactive protein (CRP) should also be included to provide a more comprehensive picture of the anemia status of the OA children." (PMID 37007386, 2023). "Multiple factors secondary to renal dysfunction, including anemia, elevated C-reactive protein level, inflammation, electrolytes disturbances and accumulation of uremic toxins contribute to the damage of cerebral microvessels, and direct neuronal toxicity." (PMID 36600230, 2023). "A malignancy history lowers a participant's HALP score even when adjusting for sex, age, baseline CRP, anemia treatment in the last 3 months, kidney failure, and current cigarette use/smoking." (PMID 37284646, 2023). "Lab evaluations revealed anemia, elevated white cell count, and c-reactive protein along sterile pyuria." (PMID 37378132, 2023). "The laboratory characteristics of NP are mainly associated with mild-to-moderate anemia, hypoalbuminemia and elevated inflammatory markers, like white blood cell (WBC) counts and C-reactive protein (CRP) levels." (PMID 36983257, 2023). "She had a new normocytic anemia (hemoglobin 85 g/L) and her C-reactive protein (CRP) had climbed from < 5 to 24 mg/L." (PMID 37024963, 2023). "The third patient presented fever, cervical lymphadenopathy, abdominal pain, hepatomegaly, pericardial effusion, anemia, neutropenia, lymphocytosis, elevated C-reactive protein, fibrinogen, lactic acid dehydrogenase and positive SARS-CoV-2 PCR." (PMID 37848930, 2023). "At that time, the patient had normal stool, normal CRP, liver enzyme, fibrinogen, and D-dimer levels, and normocytic anemia (hemoglobin level of 103 g/L)." (PMID 36984577, 2023). "In line with previous studies, the most consistent laboratory features in patients with abdominal TB were anemia, elevated CRP, and elevated ESR." (PMID 36229559, 2023). "All patients showed anaemia, elevated CRP protein, and ESR levels, and one had an increased white blood cell (WBC) count." (PMID 38259974, 2023). "In conclusion, among patients who receive chemotherapy in an outpatient setting, those with anemia and high CRP level tend to develop fatigue." (PMID 36803913, 2023). "When excluding those with possible inflammation (n = 215, CRP> 5 mg/L), 129 women had anemia of which only 35 (27.13%) had also low ferritin values." (PMID 37963155, 2023).
anemia (continued). "In this study, anemic patients were more likely to present with increased levels of C-reactive protein, procalcitonin, lactate dehydrogenase, and ferritin, thus suggesting that the most likely pathophysiological mechanism leading to anemia was inflammation." (PMID 37270578, 2023). "Laboratory abnormalities are also common, including anemia, thrombocytopenia, high serum CRP, low serum albumin and hyperglobulinemia." (PMID 37784011, 2023). "Most patients had severe anaemia (58.5%), lymphopenia (81.3%), and high levels of C-reactive protein (54%), D-Dimer (93.6%) and ferritin (91.2%)." (PMID 37554878, 2023). "Blood analyses revealed leucocytosis, anaemia, hypoalbuminemia, and increased lactate and C-reactive protein levels." (PMID 37700381, 2023). "In our study, it was found that anemia, hypoalbuminemia, elevated lactate dehydrogenase, glycated hemoglobin, and C-reactive protein levels are more pronounced in subjects with type two diabetes and cancer (p = 0.002)." (PMID 37627906, 2023). "Apart from these previous episodes, he also suffered from systemic lymphadenopathy, anemia, elevated C-reactive protein, polyclonal hypergammopathy, and elevated interleukin (IL)-6." (PMID 36873956, 2023). "The laboratory findings from that time showed anemia and elevated, but decreasing c-reactive protein." (PMID 37510971, 2023). "The second patient arrived at our unit presenting fever, cervical lymphadenopathy, abdominal pain, hepatomegaly, pericardial effusion, anemia, neutropenia, lymphocytosis, elevated C-reactive protein, d-dimer, ferritin, and positive IgG SARS-CoV-2 antibodies." (PMID 37848930, 2023). "The first patient was admitted with fever, abdominal pain, nausea, vomiting, anemia, neutropenia, lymphocytosis, elevated C-reactive protein, d-dimer, ferritin, and a positive SARS-CoV-2 PCR." (PMID 37848930, 2023). "Less common signs of AIS are malaise, weight loss, hematological derangements (thrombocytopenia and resistant anemia), and elevated inflammatory markers (i.e., levels of CRP and ESR)." (PMID 37675360, 2023). "As for laboratory tests, patients should be monitored for anemia, hypoalbuminemia, and elevated C-reactive protein (CRP)." (PMID 37298350, 2023). "The most abnormalities in laboratory parameters were the elevation of C-reactive protein (CRP) level, followed by decreased mineral density, anaemia, and hypoalbuminemia." (PMID 37064636, 2023). "His initial blood tests revealed elevated levels of platelets, leukocytes, and C-reactive protein (CRP) and anemia." (PMID 37554596, 2023). "In KDSS, systemic inflammatory markers, such as anemia, thrombocytopenia, CRP elevation, hypoalbuminemia, or hyperferritinemia, are more frequent and more severe compared with KD." (PMID 37761488, 2023). "Blood tests showed increased ESR (88 mm/h) and CRP (156.3 mg/L), anemia (Hb 10.6 g/dL) and neutrophilic leukocytosis (WBC 24530/μl, N 20710/μl)." (PMID 37848930, 2023). "In this context we describe and discuss the effects of aging on normal hematopoiesis together with the occurrence of anemia and increased C-reactive protein (CRP) levels in elderly individuals." (PMID 35160156, 2022). "The ACBS encompasses both neutrophilia and lymphopenia, along with anaemia and CRP, and would thus be expected as the best reflection of the IL-1β." (PMID 35027001, 2022). "Anemia, hypoalbuminemia, and elevated CRP levels indicated a poor general condition with inflammation/infection in patients with CMV esophagitis." (PMID 35329909, 2022). "In the multivariate analysis, old age, anemia, albumin and CRP levels and unidentified pathogens were significant factors for low PWR levels." (PMID 36292245, 2022). "The retained and excluded participants did not significantly vary by wealth index, maternal age, educational status, nutritional status, iron status, anemia status, CRP and status, and dietary diversity (p > 0.05)." (PMID 35883202, 2022).